PLIN1 (perilipin 1)
Description:
Modulator of adipocyte lipid metabolism. Coats lipid storage droplets to protect them from breakdown by hormone-sensitive lipase (HSL). Its absence may result in leanness. Plays a role in unilocular lipid droplet formation by activating CIDEC. Their interaction promotes lipid droplet enlargement and directional net neutral lipid transfer. May modulate lipolysis and triglyceride levels.
Synonyms: PERI; PLIN; FPLD4
Tractability: Small molecule: a high-quality ligand is known. PROTAC: its protein half-life has been measured; a small molecule that binds it is known.
Target class: Other cytosolic protein
Safety:
Unwanted effects reported when the protein is acted on. In parentheses: how it was acted on, where the effect was seen, and who reports it.
weight gain (source: ClinPGx)
Gene: Protein-coding gene on chromosome 15 (89,664,365 to 89,679,450, reverse strand). Ensembl gene ENSG00000166819.
Subcellular location: Endoplasmic reticulum; Lipid droplet
Subcellular location (Human Protein Atlas): Peroxisomes
Pathways (Reactome):
Developmental Biology: Transcriptional regulation of white adipocyte differentiation
Gene expression (Transcription): MLL4 and MLL3 complexes regulate expression of PPARG target genes in adipogenesis and hepatic steatosis
Metabolism: Triglyceride catabolism
Signal Transduction: NR1H2 & NR1H3 regulate gene expression linked to triglyceride lipolysis in adipose
Gene Ontology:
Molecular function: protein binding; lipid binding; protein sequestering activity; protein-macromolecule adaptor activity
Biological process: lipid catabolic process; lipid metabolic process; negative regulation of triglyceride catabolic process
Cellular component: endoplasmic reticulum; lipid droplet; cytosol
Genetic constraint (gnomAD): Loss-of-function variants: 37 observed, 40.52 expected, observed/expected ratio (o/e) 0.91, 90% interval 0.7 to 1.2. The synonymous counts are far from expectation, so gnomAD's model fits this gene poorly and the ratio says little. Missense variants: 776 observed, 624.56 expected, observed/expected ratio (o/e) 1.24, 90% interval 1.17 to 1.32. Synonymous variants: 340 observed, 264.91 expected, observed/expected ratio (o/e) 1.28, 90% interval 1.17 to 1.4.
Gene-disease validity (ClinGen):
ClinGen rates the evidence that PLIN1 causes each of these diseases.
PLIN1-related familial partial lipodystrophy (autosomal dominant): Definitive.
Homologues: Orthologues: chimpanzee PLIN1 (99% identical), macaque PLIN1 (95% identical), dog PLIN1 (84% identical), mouse Plin1 (82% identical), rat Plin1 (82% identical), guinea pig PLIN1 (80% identical), pig PLIN1 (78% identical), tropical clawed frog plin1 (28% identical), zebrafish plin1 (21% identical), Drosophila melanogaster Lsd-2 (12% identical). Paralogues in human: PLIN2 (21% identical), PLIN3 (20% identical), PLIN5 (20% identical), PLIN4 (15% identical).
Diseases named in the same sentence as PLIN1 in open-access papers:
PLIN1 is named in the same sentence as 116 diseases in open-access papers, as found by Europe PMC text mining. Sharing a sentence is not in itself a finding about the gene and the disease. The quoted sentences say what the papers report.
Obesity (76 papers, 2011 to 2026). Accumulation of substantial excess body fat. "There are observations of obesity‐associated initiation of lysosomal autophagy in adipocytes leading to the degradation of PLIN1." (PMID 40526038, 2025). "Another study of the rs1052700 variant of the PLIN1 gene showed an association with increased obesity in the Caucasian population." (PMID 39458556, 2024). "A result of their elevated basal lipolysis rate, PLIN1-deficient mice exhibit resistance to diet-induced obesity." (PMID 39030618, 2024). "The depletion of PLIN1 and mutation of the leptin receptor gene can help to prevent obesity, given that PLIN1 deficiency induces an inflammatory response in fat through the dysregulation of lipolysis." (PMID 39139927, 2024). "An analysis of several SNP variants (rs2289487, rs1561726, rs2304794, rs894160, rs2304795, rs1052700) in the PLIN1 gene was conducted to assess their significance in obesity on weight loss and glucose metabolism." (PMID 39458556, 2024). "Previous studies have shown that FTO and PLIN1 do not only play a role in regulating obesity; they are also significantly associated (p < 0.05) with economically important traits in pigs, sheep, and cattle." (PMID 37835645, 2023). "Among the many genes known to influence morphometric traits, the FTO (fat mass and obesity-associated) and PLIN1 (perilipin 1) genes have gained attention due to their involvement in adipogenesis and lipid metabolism in the PPAR signaling pathway." (PMID 37835645, 2023). "The PLIN1 (rs1052700) is an obesity risk factor, which is also associated with better weight loss outcomes." (PMID 36986146, 2023). "PLIN1 is a phosphorylatable phosphoprotein associated with lipid droplets; it is involved in lipid catabolism, which is also linked to obesity." (PMID 37835645, 2023). "To date, several studies have confirmed the association of PLIN1 SNPs with the risk of obesity, insulin resistance, diabetes mellitus, higher body weight and hypertension." (PMID 32803726, 2021). "PLIN1 is also associated with an excessive bodyweight risk and complications of obesity (e.g., insulin resistance or different metabolic disorders)." (PMID 34208363, 2021). "Despite these findings, to date, no consensus has been reached on the mechanisms underlying the obesity-associated downregulation of PLIN1." (PMID 31959889, 2020). "For example, the reduced expression of PLIN1 protein in obesity was associated with the promotion of inflammatory responses." (PMID 31959889, 2020). "PLIN1 knockout increases basal lipolysis, decreases LD size in adipocytes, and causes resistance to diet-induced obesity in mice." (PMID 29593725, 2018). "The effect of arsenic or the inhibition of these receptors can modulate the perilipin 1 (PLIN1) expression and lipolysis and, therefore, obesity risk and its consequences." (PMID 25799405, 2015). "Novel high impact variants resulting in premature stop codons were identified in the following genes associated with enriched obesity pathways in Meishan pigs: PLIN1 (adipogenesis, white adipose tissue browning), GRB10 (insulin receptor signaling), and ACOT4 (stearate biosynthesis I)." (PMID 40340757, 2025). "Interestingly, PLIN1 overexpression causes adipose tissues to shrink and imparts resistance to diet-induced obesity." (PMID 39030618, 2024). "Similarly, PLIN1 polymorphism has also been shown to lead to an increased risk of obesity, As the patients in these studies were in the child population and genetic polymorphisms were investigated, it is difficult to compare the data with this study." (PMID 39062220, 2024). "In addition, a haplotype of two SNPs of the PLIN1 gene, 13041A>G (rs2304795) and 14995A>T (rs1052700), has previously been associated with obesity risk and with response to a 6-month endurance exercise intervention." (PMID 34539437, 2021).
Obesity (continued). "For the related PLIN1, one study demonstrated that obesity and highlipolysis rates are independently associated with lower PLIN1 protein levels inwomen, whereas another demonstrated reduced levels of both PLIN1mRNA and protein in obese compared to non-obese subjects." (PMID 21533135, 2011). "In addition, Plin1-KO mice exhibited high basal lipolysis because of the loss of the protective function of Plin on LDs, thus resulting in a reduction in TG deposits, glucose intolerance, and resistance to diet-induced obesity." (PMID 39859272, 2025). "Animal studies have found that amidation-modified Apelin-13 might significantly reduce the average diameter of adipocytes, mRNA and protein expression of peroxisome proliferator-activated receptor γ (PPARγ) levels and perilipin 1 (PLIN1), thereby improving the dyslipidemia caused by obesity." (PMID 38089606, 2023). "Among SNPs, rs2304795 (13041A>G) located in the 3′ region of the PLIN1 gene seems to have a significant role in the regulation of perilipin function and adipose tissue turnover in the body, as its close association with BMI, body weight and obesity risk has been reported." (PMID 32803726, 2021). "Firstly, we detected expression levels of key adipogenesis genes, such as CEBPA, PPARG, lipoprotein lipase (LPL), fatty acid binding protein 4(FABP4) and perilipin 1 (PLIN1), which play critical roles in the development of obesity." (PMID 39773638, 2025). "Plin1 is highly expressed in obese individuals and is considered a significant factor in human obesity." (PMID 40904782, 2025). "Plin1 deficiency leads to increased lipolysis, hence Plin1 knock-out mice are lean, show reduced LD size, are resistant to HFD-induced obesity, and develop insulin resistance." (PMID 38514628, 2024). "Despite the similar anti-obesity effects in knockout and overexpression models, PLIN1 adipose overexpression enhances glucose tolerance and insulin sensitivity, but its deficiency causes the opposite effects in mice." (PMID 39030618, 2024). "As mentioned in the obesity section, proteins like PLIN1 and CIDEC affect leptin production and insulin sensitivity." (PMID 39030618, 2024). "In this regard, Plin1 KO mice had lower adipose mass and were resistant to diet-induced obesity but developed glucose intolerance and insulin resistance." (PMID 38167864, 2024). "PLIN1 gene knockout mice show obesity resistance, potentially due to inflammation of tissue inflammation and insulin resistance, driven by increased recruitment of inflammatory macrophages." (PMID 39030618, 2024). "PLIN1 is located on chromosome 15q26, a chromosomal location connected with obesity, impaired glucose metabolism, and hypertriglyceridemia." (PMID 36986146, 2023). "Data from different studies indicate that the genetic effect of PLIN1 depends on obesity and adipokine secretion, which can negatively impact adipose tissue endocrine function and lead to diabetes." (PMID 35886029, 2022). "Another mechanism of the development of obesity is observed in the case of SNPs located in the perilipin-1 gene (PLIN1)." (PMID 36613286, 2022). "PLIN1, perilipin-1, has been considered as a candidate gene that contributes to the polygenic disease phenotype of human obesity." (PMID 35692369, 2022). "For each participant, three SNPs in three genes (FTO rs9939609, TFAP2B rs987237, PLIN1 rs894160) related to obesity were genotyped." (PMID 36142109, 2022). "The results of Oil red O staining and adipocyte-specific genes (Pparg, Plin1, and Insr) expression detection indicated that the adipogenic differentiation potential of ASCs decreased in the hypertrophic obesity mice." (PMID 36035215, 2022). "PLIN1, located on lipid droplets, inhibits lipolysis and is downregulated in adipose of subjects with obesity." (PMID 34394003, 2021). "Here the authors report that O-GlcNAc transferase inhibits adipose tissue lipolysis via O-GlcNAcylation of the lipid droplet protein perilipin 1 and thus promotes diet-induced obesity." (PMID 31924761, 2020).
Obesity (continued). "Knocking down the PLIN1 gene increases basal lipolysis, reduces the size of LD in adipocytes, and leads to resistance to diet-induced obesity in mice." (PMID 33105676, 2020). "Genes of interest include the mitochondrial citrate transporter Slc25a1, as well as genes known to regulate hematopoiesis (Cd44), anaerobic glycolysis (Ldha), and obesity/lipolysis (Plin1)." (PMID 32293246, 2020). "Evidence suggests that Perilipin-1 (PLIN1) is subject to functional regulation by epigenetic modifications in women with obesity." (PMID 31807648, 2019). "This is evidenced by the phenotype of PLIN1 null mice, which have a 65–70% reduction of adipose triacylglycerol storage compared with wild-type animals and are resistant to diet-induced obesity." (PMID 30283460, 2018). "In one study, older Plin1 null mice were lean and resistant to diet-induced obesity yet developed insulin resistance." (PMID 24040030, 2013). "All these data confirmed the key role of Plin1 in LD formation and TG metabolism, together with Pcyox1, which could be an important regulator and potential therapeutic target for obesity-related disorders." (PMID 39859272, 2025). "Interestingly, however, Plin1 overexpression in adipose tissue has been reported also to protect mice against diet-induced obesity by inhibiting basal and stimulated lipolysis and to improve glucose tolerance." (PMID 38167864, 2024). "Plin1-knockout (KO) mice exhibited striking phenotypes, being lean, with microscopically reduced lipid droplet sizes in adipose tissues, increased glucose tolerance and resistance to diet-induced obesity." (PMID 36978789, 2023). "PLIN1 has also been studied in coronary artery disease and nonalcoholic fatty liver disease, which are major diseases associated with obesity." (PMID 37998612, 2023). "Interestingly, PLIN1 overexpression was found to be protective against obesity, adipocyte hypertrophy, and glucose intolerance in a mouse model." (PMID 37998612, 2023). "Accordingly, PLIN1 knockout mice are lean and protected from diet-induced obesity." (PMID 33105676, 2020). "Several studies have demonstrated that obesity reduces PLIN1 expression." (PMID 31959889, 2020). "The mutation of perilipin 1 in mice results in a lean phenotype, and a lack of perilipin 1 combined with a mutation in the leptin receptor gene in mice reverses obesity." (PMID 27136547, 2016). "Two perilipins have been characterized in flies: Lsd-2 promotes fat storage as mutants of Lsd-2 are lean and starvation sensitive; and perilipin-1 mutants display adult onset obesity and hyperphagia, suggesting a role for this molecule in controlled access of the lipid droplets to lipolytic enzymes." (PMID 23587196, 2013). "Thus, we suggest that CMA and the release of CTSB accompanying LMP might play a role in PLIN1 degradation at the early and advanced stages of obesity, respectively." (PMID 31959889, 2020). "Taken together, our results revealed (i) a novel RXRα-mediated mechanism by which transcription of the chicken PLIN1 gene is regulated and (ii) the role of RXRα in adipogenesis, which may allow us to identify novel therapeutic strategies to protect against obesity." (PMID 32478078, 2020). "Studies on patients with obesity and T2DM have shown a positive correlation between PLIN1, CIDEC, and BMI in abdominal subcutaneous (SAT) and visceral adipose tissues." (PMID 39030618, 2024). "In point of fact, PLIN1 deletion has been shown to minimize weight gain in HFD db/db mice and proposed as an obesity preventive mediator." (PMID 38146533, 2023). "These assays resulted in two distinct patterns for PKP2 gene expression, segregated by fat depot and the obesity state, and matching those of adipogenesis-regulated genes, such as ADIPOQ, PLIN1, and FASN." (PMID 37607954, 2023). "Overall, additional studies will be needed to shed light on the role of perilipin-1 on AQP3 functionality under physiological conditions and metabolic diseases, such as obesity." (PMID 36077012, 2022).
Obesity (continued). "Therefore, we hypothesized that PLIN1 protein in obese WAT is degraded by increased CTSB in adipocytes at the early stage of obesity, and that increased PLIN1 protein degradation and reduced PLIN1 gene expression contribute to the net protein loss in the late stage of obesity." (PMID 31959889, 2020). "PLIN1, an essential protein for lipid storage and lipolysis, can be ubiquitinated and then degraded through SQSTM1-mediated autophagy under obesity-related inflammatory states." (PMID 30741926, 2019). "Although SNPs were located on obesity-related genes, some of the genes also have a direct role in lipid metabolism including PPARG, FABP2, PLIN1, NPC1, ACSL5, and FAAH, suggesting relationships between genetics, adiposity, and plasma lipid profiles." (PMID 30581838, 2018). "On day 4, the network showed inhibition of the upstream regulator N-CoR in BPS-treated cells which leads to activation of adipogenic genes such as SCD, PLIN1, ACACB, CIDEC, ADIPOQ and FABP, leading to obesity." (PMID 27685785, 2016). "Our results indicate that HPWE treatment attenuates the expression of PLIN1 and ATF-3, thereby supporting the hypothesis that HPWE exerts anti-obesity effects in vitro." (PMID 41155164, 2025). "Obesity is a polygenic disease whose pathogenesis involves the FTO, PLIN1, TRAP2B, and BDNF genes." (PMID 36613286, 2022). "This study proposes an important mechanism of PLIN1 regulation and the possibility that CTSB might be a novel therapeutic target for obesity." (PMID 31959889, 2020). "Interestingly, the reductions of PLIN1 and FASN expression are individually reported as improving resistance to HG-induced obesity and insulin sensitivity and reducing adipose tissue inflammation." (PMID 33003504, 2020). "PLIN1 was established for a distinct role in regulating both TAG storage and lipolysis in adipocytes and was regarded as a candidate gene contributing to human obesity." (PMID 26703591, 2015). "Therefore, HSL and PLIN-1 involved in the lipolytic process are likely target proteins of physical activity in the non-pharmacological treatment of metabolic syndrome and obesity." (PMID 39954126, 2025). "Therefore, the upregulation of basal FFA released via CTSB-induced PLIN1 degradation in adipocytes might contribute to a chronic state of low-grade inflammation, which is usually observed in obese WAT, leading to a pathological state of obesity." (PMID 31959889, 2020). "Cells isolated from elderly subjects with or without obesity were significantly impaired in their capacity to differentiate into adipocytes, as revealed by Oil Red O staining of neutral lipids and by the gene expression of common adipogenic markers (PPARG, FABP4, LPL, PLIN1, and FASN)." (PMID 35811457, 2022).